VDR (vitamin D receptor)
Diseases named in the same sentence as VDR in open-access papers (continued):
Sharing a sentence is not in itself a finding about the gene and the disease.
colorectal cancer (continued). "Distribution of VDR SNPs genotype and allele frequencies in colorectal cancer cases and control population based on gender." (PMID 27309378, 2016). "In this study, 8 VDR SNPs, 5 of which were located in the 3′ region, were nominally associated with the risk of colorectal cancer." (PMID 27736940, 2016). "Overall, the findings of this study provide only limited support for an association between common genetic variations in VDR and colorectal cancer risk in the Japanese population." (PMID 27736940, 2016). "Several investigations have focused on the association of genetic variants in the VDR gene and predisposition of colorectal cancers in different populations." (PMID 27309378, 2016). "Here, we aimed to evaluate the associations between common variation in the VDR gene and colorectal cancer risk using a comprehensive tag SNP approach." (PMID 27736940, 2016). "Distribution of VDR SNPs genotype and allele frequencies in colorectal cancer cases and control population." (PMID 27309378, 2016). "Genetic variants in the VDR gene have been associated with several cancers in different population including colorectal cancer." (PMID 27309378, 2016). "In summary, the findings of this nested case-control study among a Japanese population provides only limited support for an association between common variations in the VDR gene and colorectal cancer risk." (PMID 27736940, 2016). "Distribution of VDR SNPs genotype and allele frequencies in colorectal cancer cases and control population based on age." (PMID 27309378, 2016). "The relationship between polymorphisms of the VDR gene and sporadic colorectal cancer has been previously studied." (PMID 25195132, 2014). "The aim of our study was to investigate four polymorphisms, BsmI, ApaI, TaqI, and FokI, of the VDR gene in Polish patients with sporadic colorectal cancer and to evaluate their association with the risk of cancer." (PMID 25195132, 2014). "The aim of our study was to investigate four polymorphisms, BsmI, ApaI, TaqI, and FokI, of the VDR gene in Polish patients with sporadic colorectal cancer and to evaluate their association with susceptibility to cancer." (PMID 25195132, 2014). "The risk of colorectal cancer, the cancer most strongly associated with VDR, more than doubles when individuals carrying the ff genotype of FokI consume a low-calcium or low-fat diet, compared to FF genotypes." (PMID 23805323, 2013). "There appears to be some conflict in the literature regarding VDR relationship, as it has been studied to be associated with various cancers, including colorectal carcinoma." (PMID 27942313, 2011). "In contrast, a US case-control study reported increased colorectal cancer risk with increasing vitamin D intake for subjects with the homozygous variant VDR (BsmI BB) allele." (PMID 20049159, 2010). "Concordantly, a high level of VDR expression is associated with a favourable prognosis in colorectal cancer." (PMID 15770204, 2005). "Similarly, single-nucleotide polymorphisms (SNPs) in the vitamin D receptor (VDR) gene can affect the efficacy of vitamin D therapy in colorectal cancer patients." (PMID 40909085, 2025). "Genetic variations in the VDR gene (FokI, BsmI, ApaI, TaqI, Cdx−2, Tru9I) have been significantly linked to several types of cancer including prostate, breast, skin, bladder, ovarian, hepatocellular carcinoma, and colorectal cancer." (PMID 39451780, 2024). "SNPs in the vitamin D receptor gene have also been linked to decreased risk in prostate cancer in African American men and rs1866074 near the thymine DNA glycosylase gene were reported to be correlated with lower colorectal cancer risk." (PMID 32881892, 2020). "This also applies to the role of VDR polymorphisms in colorectal cancer (CRC)." (PMID 31534963, 2019). "Additionally, several previous studies have examined the VDR FokI variant in relation to colorectal adenoma, a precursor lesion for colorectal cancer." (PMID 30150667, 2018).
colorectal cancer (continued). "Therefore, a systematic meta-analysis was performed to combine data from previous studies on the association between VDR FokI polymorphism and the risks of colorectal diseases, including colorectal cancer, colorectal adenoma, and inflammatory bowel disease." (PMID 30150667, 2018). "Eight VDR SNPs, namely rs2254210, rs1540339, rs2107301, rs11168267, rs11574113, rs731236 (TaqI), rs3847987 and rs11574143, the latter 5 of which were located in the 3′ region, were nominally associated with the risk of colorectal cancer." (PMID 27736940, 2016). "Although the VDR gene is large (>100 kb), and a number of single nucleotide polymorphisms (SNPs) have been discovered in it, only a few comprehensive analyses have captured a large fraction of common SNPs in VDR in relation to colorectal cancer." (PMID 27736940, 2016). "High levels of VDR in colorectal cancer have also been associated with improved survival." (PMID 23346460, 2012). "In particular, vitamin D may affect colorectal cancer (CRC) risk via its binding to the vitamin D receptor (VDR) influencing cell proliferation, differentiation, apoptosis and angiogenesis or affecting insulin resistance." (PMID 22701574, 2012). "However, our study showed that cumulative methylation level of significant CpG sites in VDR was inversely associated with colorectal cancer risk, which was inconsistent with our hypothesis." (PMID 37644572, 2023). "For example, vitamin D3 is known to protect against colorectal cancer by suppressing epithelial cell proliferation and inducing apoptosis, while increased apoptotic cell death was observed in the small intestine and colon of vitamin D receptor (VDR)-deficient mice." (PMID 33985576, 2021). "Due to the high prevalence of colorectal cancers in Saudi Arabian population, we examined four commonly studied polymorphic loci, rs1544410 (BsmI), rs2228570 (FokI), rs7975232 (ApaI) and rs731236 (TaqI) in the VDR gene for a possible association with the risk of developing this malignancy." (PMID 27309378, 2016). "Among the results, eight VDR SNPs, namely rs2254210, rs1540339, rs2107301, rs11168267, rs11574113, rs731236, rs3847987 and rs11574143, the latter 5 of which were located in the 3′ region, were nominally associated with the risk of colorectal cancer (P = 0.01–0.048)." (PMID 27736940, 2016). "KRT19, KRT20, and VDR, which are markers of colonic enterocytes, were increased in reverted colorectal cancer cells." (PMID 39661721, 2025). "Evidence in lung cancer is inconsistent, but high VDR expression in the gastrointestinal tract suggests a role for vitamin D in colorectal cancer progression and prognosis." (PMID 41515234, 2025). "VDR is upregulated in all gynecological malignancies, whereas reduced expression has been observed in colorectal cancer." (PMID 40872626, 2025). "Research has demonstrated that probiotics such as LGG and L. plantarum enhanced the expression of VDR protein and L. plantarum alone increased VDR transcriptional activity in Human Colorectal Carcinoma Cell Line 116 (HCT116) cells." (PMID 40534849, 2025). "It has been reported that high expression of VDR in tumor stromal fibroblasts was correlated with favorable prognosis in colorectal cancer." (PMID 38639057, 2024). "A study in patients with colorectal cancer reports a decrease in serum levels of VDR compared to control subjects (0.49 ± 0.13 ng/mL vs. 4.08 ± 0.43 ng/mL, p < 0.0001)." (PMID 38397875, 2024). "The study showed that treatment with the biologically active form of vitamin D (1,25(OH)2D3) increases NAT2 expression and that VDR binds to the NAT2 promoter in colorectal cancer cells." (PMID 39624836, 2024). "In fact, tumor growth of the colon adenocarcinoma cell line SW480 in mice is impaired when cells overexpress VDR, indicating that VDR acts as a tumor suppressor in colorectal cancer." (PMID 38666921, 2024).
colorectal cancer (continued). "It has been reported that Carnobacterium colonizes the gut in an estrogen-dependent manner and collaborates with other microbes to increase the production of vitamin D in the intestinal tract, activating the host VDR and suppressing colorectal cancer." (PMID 39195789, 2024). "ASP inhibited epithelial-mesenchymal transition (EMT) by regulating the vitamin D receptor (VDR)/Smad3 pathway, thereby preventing the occurrence of colorectal cancer." (PMID 38896161, 2024). "This study indicated that the cumulative methylation levels of significant CpG sites in VDR and CYP24A1 and all CpG sites in CYP2R1 were inversely associated with colorectal cancer risk." (PMID 37644572, 2023). "In contrast, no statistical association was found between the methylation status of VDR, CYP24A1, and CYP27B1 at all CpG sites and the risk of colorectal cancer." (PMID 37644572, 2023). "VDR can inhibit glycolysis in colorectal cancer, and VD supplementation can improve mitochondrial respiration in primary trophoblasts isolated from obese women." (PMID 36909229, 2023). "Significant inverse association was observed between cumulative methylation level of significant CpG sites in VDR (aOR, 0.28; 95% CI, 0.16–0.51) and CYP24A1 (aOR, 0.19; 95% CI, 0.09–0.40) and colorectal cancer risk." (PMID 37644572, 2023). "A beneficial role of vitamin D and VDR, related to their activity on stromal fibroblasts, was reported in patients with colorectal cancer (CRC), in whom increased VDR expression in stromal tumor fibroblasts was associated with better survival." (PMID 37175993, 2023). "A study conducted by Afshan and colleagues in 75 colorectal cancer samples detected the hypermethylation of the VDR promoter in 28 (37.33%) of 75 cases." (PMID 38203278, 2023). "There were significant inverse associations between cumulative methylation levels of significant CpG sites in VDR and CYP24A1 and colorectal cancer risk." (PMID 37644572, 2023). "In this context, we conducted this study to examine the association between methylation levels of four vitamin D metabolic pathway-related genes (VDR, CYP24A1, CYP27B1 and CYP2R1) from blood and the risk of colorectal cancer." (PMID 37644572, 2023). "The cumulative methylation levels of significant CpG sites in VDR and CYP24A1 and all CpG sites in CYP2R1 were inversely associated with colorectal cancer risk." (PMID 37644572, 2023). "One study explored the difference of the methylation frequency of VDR, one of the vitamin D metabolic pathway-related genes, between tumor and normal tissue in colorectal cancer cases." (PMID 37644572, 2023). "Another study confirmed that VDR expression is associated with the PI3K-AKT pathway and KRAS mutation in colorectal cancer." (PMID 37561808, 2023). "Colorectal cancer is a third example in which the role of VDR promoter hypermethylation has been investigated." (PMID 38203278, 2023). "MeTC7 inhibits radiotherapy (RT)-induced PD-L1 expression in vivo: MC38 colorectal cancer cell-based syngeneic animal model in which VDR and PD-L1 overexpression co-occurs under radiation therapy was employed to estimate the efficacy of MeTC7." (PMID 37444542, 2023). "For example, a Spanish study collected visceral adipose tissues (VAT) from 57 patients with colorectal cancer and 50 healthy controls to explore vitamin D receptor (VDR) expression and methylation in colorectal cancer." (PMID 35475772, 2022). "Decreased methylation status of VDR in colorectal cancer tissue correlated with longer overall survival." (PMID 36246903, 2022). "Methylation specific PCR of colorectal cancer tissue vs surrounding healthy tissue showed that hypermethylation of VDR inversely correlates with VDR expression and it is associated with tumor staging." (PMID 36246903, 2022). "In particular, primary pancreas, prostate, breast and colorectal cancer cells demonstrated a reduced VDR expression compared to benign tissues, implying that VDR expression is dysregulated in cancer cells." (PMID 36362766, 2022).
colorectal cancer (continued). "In this regard, high levels of p62 are correlated with a decrease in the levels of VDR in colorectal cancer, probably mediated by selective autophagy degradation." (PMID 33634029, 2020). "The authors showed that through its direct interaction, p62/VDR contributed to the pro-tumorigenic properties of two cell lines of colorectal cancer (SW480 and HCT116), promoting tumor progression in vivo." (PMID 33634029, 2020). "VDR can improve colorectal cancer prognosis by inducing differentiation, promoting apoptosis, inhibiting cancer development and growth, and decreasing cancer cell proliferation and tumor angiogenesis." (PMID 31850208, 2019). "Butyrate not only suppressed NF-κB activation, but also modulated the activity and expression of the Peroxisome-Proliferator-Activated-Receptor gamma (PPARγ) and the vitamin D receptor (VDR) in colorectal cancer cells." (PMID 31067776, 2019). "Supporting this function, genetic ablation of VDR in mice increases development of colorectal cancers." (PMID 28702373, 2017). "Calcitriol binds to the vitamin D receptor (VDR), which regulates the expression of several genes involved in colorectal cancer, such as BIRC5, CDKN1A, CDH1 or HIF1α." (PMID 26158294, 2015). "A recent study suggested that in colorectal cancer metastases, VDR becomes the target of the polycomb group protein enhancer of zeste homolog 2 (EZH2) that mediates VDR downregulation by H3K27 trimethylation in the VDR promoter." (PMID 24808866, 2014). "This can be interpreted as activation of the 1,25-(OH)2D3/VDR complex in response to inflammatory stimuli in colorectal cancer tissue." (PMID 24213465, 2012). "An attractive, albeit unexplored, possibility is the study of SNAIL or VDR RNA levels in blood, a strategy used for cytokeratin 19, carcinoembryonic antigen and β-catenin in colorectal cancer and other genes in different neoplasias." (PMID 15770204, 2005). "Preclinical data suggest that overexpression of the vitamin D receptor (VDR) may interact with the RAS-MAPK and PI3K-AKT pathways in colorectal cancer, supporting the potential for chemoprevention strategies targeting VDR." (PMID 41425618, 2025). "Available evidence suggests that vitamin D and its non-hypercalcemic analogues could be used in the prevention or adjuvant treatment of colorectal cancer, particularly in early stages or in patients with high VDR expression." (PMID 41301826, 2025). "Vitamin D receptor (VDR) plays a role in preventing the progression of colorectal cancer (CRC) and may be a crucial mediator of the anticancer effects produced by certain alkaloids." (PMID 41150758, 2025). "VDR plays a crucial role in both colorectal cancer (CRC) and ulcerative colitis (UC)." (PMID 40791849, 2025). "Our results suggest that hypomethylation of significant CpG sites in VDR maybe a potential biomarker of colorectal cancer." (PMID 37644572, 2023). "Only two studies reported the association between VDR expression and CSS in patients with digestive system tumours: one related to oesophageal cancer, which included 130 patients, and another on colorectal cancer, which included 599 patients." (PMID 37561808, 2023). "Additionally, utilizing a syngeneic colorectal cancer model in which VDR/PD-L1 co-upregulation occurs in vivo under radiation therapy (RT), MeTC7 inhibits PD-L1 and enhances intra-tumoral CD8+T cells expressing lymphoid activation antigen-CD69." (PMID 37444542, 2023). "We hypothesized that the methylation level of CYP24A1 could be negatively associated with colorectal cancer risk, while the methylation levels of VDR, CYP2R1 and CYP27B1 could be positively associated with colorectal cancer risk." (PMID 37644572, 2023). "The biological functions of VDR have been investigated in colorectal cancer." (PMID 37561808, 2023). "Furthermore, methylation levels and decreased VDR expression were correlated with the different grades and stages of carcinoma progression, from poorly differentiated colorectal cancer to advanced stages." (PMID 38203278, 2023).
colorectal cancer (continued). "Based on this, we screened published studies related to VDR expression and prognosis of malignant tumours and included eight related studies on digestive system tumours (three on colorectal cancer, three on oesophageal cancer, one on pancreatic cancer, and one on cholangiocarcinoma)." (PMID 37561808, 2023). "Similarly, in colorectal cancer cells, calcitriol treatment was shown to inhibit the activation of CAFs, and VDR expression in fibroblasts of the tumor stroma correlated with increased overall survival in patients." (PMID 34330705, 2021). "miR-675–5p has been reported to regulate VDR expression in colorectal cancer cells, whereas miR-627 has been demonstrated to suppress mouse colorectal cancer cells proliferation via histone demethylase 1A (JMJD1A) downregulation, suggesting a crucial role in cancer control." (PMID 32560347, 2020). "In another case-control study of a US population, the interaction between SNPs or haplotypes within the VDR gene and dietary factors did not affect the risk of colorectal cancer." (PMID 31167402, 2019). "Some, but not all, studies within colorectal cancer patients have demonstrated that higher VDR expression is associated with improved survival." (PMID 30344947, 2018). "Recent studies have reported the associations between vitamin D receptor (VDR) polymorphisms and colorectal cancer (CRC), but the results were not always consistent." (PMID 29560132, 2018). "Another interesting feature of previous studies in other cancer sites was that higher VDR expression was more frequently observed in well differentiated tumours compared to poorly differentiated tumours in colorectal cancer, pancreatic adenocarcinoma and cholangiocarcinoma." (PMID 30344947, 2018). "In-vitro studies within colorectal cancer cell lines have demonstrated that cells with high VDR expression tend to be well differentiated and are biologically favourable, whereas cell lines with low VDR expression demonstrated aggressive features with higher metastatic potential." (PMID 30344947, 2018). "We did not observe significant association of any of the four VDR polymorphisms with colorectal cancer risk in the overall analysis." (PMID 27309378, 2016). "This can in part explain the lack of association of the VDR SNPs in the overall analysis in this study compared to those who observed significant association with colorectal cancers in their populations." (PMID 27309378, 2016). "In the overall analysis, none of the four genetic variants in the VDR gene were found to be significantly associated with risk of developing colorectal cancer." (PMID 27309378, 2016). "Secondary bile acids solve the puzzle of colorectal cancer because they sit at the crossroad of nutritional and hormonal signals modulating the tangled interactions between the environmental factors, such as diet, and the nuclear receptors such as VDR." (PMID 24884764, 2014). "The protective effect of vitamin D against several cancers including colorectal cancer is modulated by the vitamin D receptor (VDR) and its ligand, the active form of vitamin D. VDR response has been found to play a role in various genes encoding proteins involved in crucial cellular pathways." (PMID 25195132, 2014). "Several studies suggest that cellular effects of VDR may be associated with MAPK signaling pathways, especially KRAS mutation in several cancer types such as breast and colorectal cancers." (PMID 23691496, 2013). "While others suggested that significant associations with VDR polymorphisms was found not in colorectal cancers but much stronger in cancers of breast, prostate and renal cell carcinomas." (PMID 22206623, 2011). "Furthermore, we show 1,25(OH)2D3 increases TCF-4 at the RNA and protein levels in several human colorectal cancer cell lines, the effect of which is completely dependent on the VDR." (PMID 19924301, 2009).